MITF (melanocyte inducing transcription factor)
Diseases named in the same sentence as MITF in open-access papers (continued):
Sharing a sentence is not in itself a finding about the gene and the disease.
melanoma (continued). "Collectively, these results suggest that 7-MSI activates the ERK signaling pathway, resulting in activation of the autophagy system and degradation of MITF, which downregulates the expression of melanogenesis-associated proteins in melanoma cells." (PMID 33672463, 2021). "TNFα also promotes melanoma dedifferentiation by suppressing the expression of the microphthalmia-associated transcription factor (MITF), a master regulator of the pigmentation pathway and melanocytic antigens, including the TRP1, DCT and MLANA genes." (PMID 34073253, 2021). "The master regulator of melanocyte development and a more proliferative cancer phenotype is MITF (microphthalmia-associated transcription factor), which expression is distinctive for melanoma-initiating cells." (PMID 33918883, 2021). "Melanomas that are high for the Microphthalmia-associated transcription factor (MITF), which promotes aggressive proliferation but suppresses invasion, are dependent upon SCD1, perhaps to sustain membrane lipid biosynthesis." (PMID 34649956, 2021). "We demonstrated here that the loss of MIcrophthalmia associated Transcription Factor (MITF), a pivotal player in melanocyte differentiation, favors the escape of melanoma cells from the immune system." (PMID 33413419, 2021). "A key determinant of melanoma phenotype is the expression and activity of the microphthalmia-associated transcription factor MITF." (PMID 33789714, 2021). "Individuals harboring MITF germline pathogenic variants are at increased risk of developing cancer, most notably melanoma and renal cell carcinoma." (PMID 34289891, 2021). "Since ADAM10 suppresses the presentation of the NKG2D ligands for NK cells on the melanoma cell surface, loss of either MITF or ADAM10 increased ligand expression and consequently greatly increased NK cell-mediated cell death." (PMID 33789714, 2021). "MITF is closely associated with plasticity in melanoma, and reportedly regulates PPARGC1A (also known as PGC1A), which in turn has a net effect of shifting metabolism towards oxidative phosphorylation." (PMID 34831420, 2021). "MITF is a melanocyte lineage-specific transcription factor that is linked to plasticity of melanoma cells and has key roles in proliferation, migration, and invasiveness of melanoma cells." (PMID 33647315, 2021). "Microphthalmia-associated transcription factor (MITF) is an essential molecule for melanocyte proliferation and survival, which plays a key role in melanoma progression." (PMID 33321449, 2021). "Disrupted in Renal Carcinoma 3 (DIRC3) lncRNA is transcriptionally repressed by microphthalmia-associated transcription factor (MITF)- SRY-box transcription factor 10 (SOX10) pathway in melanoma." (PMID 34638331, 2021). "The rheostat model predicts that MITF loss should reduce cell proliferation but increase migration potential of melanoma cells." (PMID 33438577, 2021). "Specifically, loss of MITF is an indication of dedifferentiation of melanoma, which is supported by enhanced migration/invasion gene expression profiles." (PMID 37849907, 2021). "Western blotting, confocal microscopy, flow cytometry, and natural killer (NK) cytotoxicity assays were used to determine the underlying mechanisms by which MITF-driven phenotypic plasticity modulates melanoma NK cell-mediated killing." (PMID 33789714, 2021).
melanoma (continued). "Nevertheless, SUMOylation of the MITF is paramount for melanoma pathogenesis, as patients with a germline mutation that prevents K316 SUMOylation have an increased risk of developing melanoma." (PMID 33800394, 2021). "These AC-null cells exhibited strong down-regulation of Microphthalmia-associated transcription factor (MITF), a key regulator of melanocyte development that plays a central role in melanoma progression." (PMID 33806766, 2021). "Microphthalmia-associated transcription factor (MITF) is the principal transcription factor regulating pivotal processes in melanoma cell development, growth, survival, proliferation, differentiation and invasion." (PMID 34356645, 2021). "An interesting study outlined the effect of VIP on B16F10 mouse melanoma cells, increasing microphthalmia-associated transcription factor (MITF) but also tyrosinase activity." (PMID 34068618, 2021). "The switch was ERK dependent, and the expression of the melanoma-specific transcription factor and oncogene MITF (melanoma-associated transcription factor) was decreased." (PMID 34063141, 2021). "These microRNAs included 2/2 ‘MITF-low’-, 10/13 ‘keratin’- and 1/4 ‘immune’-associated microRNAs that were identified in the original analysis of TCGA melanoma metastatic lesions." (PMID 34771465, 2021). "Microphthalmia-associated transcription factor (MITF) is a transcription factor that is required for metastasis in melanoma animal models, and its depletion from melanoma cells decreased lung metastasis." (PMID 34207884, 2021). "IRF4 is a gene regulated by MITF in melanocytic cells, and it was also found to have a functional variant associated with increased Breslow thickness, conferring a worse survival in melanoma." (PMID 35052351, 2021). "The increased MITF expression is associated with melanoma differentiation and proliferation, whereas decreased MITF expression is associated with a melanoma dedifferentiation." (PMID 33917915, 2021). "It has been observed that the mutated oncogene BRAF can regulate MITF expression, thus ensuring protein levels compatible with the proliferation and survival of melanoma cells." (PMID 34203771, 2021). "B16 mouse melanoma cells express L-PGDS under the control of microphthalmia-associated transcription factor (MITF) responsible for differentiation of melanocytes." (PMID 34744762, 2021). "This aligns with a pre-clinical model of miR-146a-5p in melanoma associated with a resistance to immunotherapy, and also highlights a potential dichotomy between ‘keratin’ and ‘MITF-low’ associated microRNAs and immunotherapy responses." (PMID 34771465, 2021). "In the Brazilian population, a study evaluating the prevalence of Germline TERT and MITF mutations in Brazilian Melanoma-Prone Patients showed an allele frequency of 0.004 in control group (1 out of 125 healthy controls) and 0,01 in melanoma patients’ cohort." (PMID 34289891, 2021). "They exhibit a clear differentiation phenotype, marked with high expression of MITF, a master regulator of melanocyte lineage differentiation and hallmark of the proliferative melanoma cell phenotype." (PMID 34604096, 2021). "Germline MITF mutations have been described to increase the risk of melanoma and, more recently, kidney cancer." (PMID 34289891, 2021).
melanoma (continued). "In contrast, USP13 also deubiquitinates and stabilises microphthalmia-associated transcription factor (MITF), an important lineage-specific master regulator in melanoma." (PMID 33627786, 2021). "For example, down-regulation of TGF-β signaling through the inhibition by MITF (Microphthalmia-associated transcription factor) can confer MEKi resistance in melanoma." (PMID 34917620, 2021). "MITF has been heavily implicated in melanoma progression, and AR-positive melanoma patients were shown to have worse prognosis because the AR promotes cell invasion through an MITF-AXL signaling axis." (PMID 33525365, 2021). "Genes involved in the epithelial-to-mesenchymal transition (EMT) process have been shown to play a role in melanoma drug resistance and have been linked to low MITF expression." (PMID 33438577, 2021). "Pigmentation and melanocyte differentiation related mutations in MC1R (melanocortin 1 receptor) and MITF (microphthalmia associated transcription factor) have also been found in melanoma." (PMID 35127523, 2021). "Mechanistically, our data show that loss/block of TPC2 results in reduced protein levels of MITF, a major regulator of melanoma progression, but an increased activity of the melanin-generating enzyme tyrosinase." (PMID 33875769, 2021). "Microphthalmia-associated transcription factor (MITF) is found to promote expression of metabolic genes in melanoma and also has a role alongside SOX10 in regulating target genes." (PMID 34249897, 2021). "Vimentin staining revealed enlarged cells, which is consistent with a report showing that loss of MITF affects the cytoskeletal structure and shape of melanoma cells." (PMID 33438577, 2021). "This approach would have an advantage in that MITF expression is maintained, enabling continued expression of MITF target genes encoding immunogenic differentiation-associated melanoma antigens such as MLANA." (PMID 33789714, 2021). "Overall, the data indicates that mutation of MITF generates a genetic predisposition for the development of melanoma and RCC." (PMID 34503213, 2021). "SAMMSON gene is located ~30 kb downstream of MITF and both genes are co-amplified in about 10% of melanomas, and amplification of both genes is associated with poor prognosis." (PMID 34638331, 2021). "MITF induces Bcl-2 expression, reducing tumorigenesis in human melanoma cells and increasing the tyrosinase expression associated with melanogenesis." (PMID 34067095, 2021). "Microphthalmia-associated transcription factor (MITF) has also been used in melanoma as an indicator of melanoma cell phenotype switching." (PMID 34066966, 2021). "DDX3X was found to regulate MITF protein levels and mutations were present in 5.8% of their melanoma cohort." (PMID 35008286, 2021). "Microphthalmia-associated transcription factor (MITF) has been reported to play a role in the progression of melanoma and other cancer types." (PMID 34208068, 2021). "In our cohort, similarly to miR-211-5p, MITF expression was also associated to longer melanoma-specific survival, findings that are supported by Mazar and colleagues." (PMID 33003444, 2020). "Recent studies have led to the identification of new genes involved in CMM susceptibility: beyond CDKN2A and CDK4, BAP1, POT1, and MITF were recently identified as potential high-risk melanoma susceptibility genes." (PMID 33322357, 2020). "In our cohort, both MITF+ patients with amelanotic/hypomelanotic melanomas carried one RHC variants." (PMID 32054529, 2020).
melanoma (continued). "The proteins encoded by MITF target genes have a strong impact on the antigenicity of melanoma cells." (PMID 32978520, 2020). "The MC1R/cAMP/MITF pathway is implicated in growth, differentiation and survival of melanocytes, as well as in malignant melanoma." (PMID 32605315, 2020). "Strong ZEB2/SLUG expression in melanoma is associated with high levels of MITF and downstream melanocyte differentiation markers." (PMID 32796736, 2020). "Melanoma-specific mechanisms almost universally involve the MIcrophthalmia-associated Transcription Factor (MITF)." (PMID 33276788, 2020). "DDX3X is an x-linked RNA helicase, which has been linked to post-translational regulation of MITF (Microphthalmia-associated Transcription Factor) expression and development of melanoma metastasis and therapy resistance." (PMID 32731355, 2020). "BRAFV600E mutation together with ectopic expression of MITF has been shown to transform primary melanocytes into malignant melanoma." (PMID 33614507, 2020). "Melanomas with activation of the mutated BRAF have suppressed levels of MITF and PGC1α and decreased oxidative metabolism." (PMID 33091721, 2020). "In fact, it has been demonstrated that melanoma phenotype switching is associated with MITF levels: High MITF levels have been found to be associated with the proliferative state while low MITF levels were associated with the invasive state." (PMID 32013263, 2020). "In primary and acquired resistance in melanoma, Axl levels inversely correlate with levels of melanocyte lineage factor- Microphthalmia-associated transcription factor (MITF)." (PMID 32092958, 2020). "This low mutation rate is nevertheless comparable to that of MITF (~2.3%), a gene known to be mutated in a subset of melanomas." (PMID 33019669, 2020). "Microphthalamia-associated transcription factor (MITF) is a critical mediator in melanocyte differentiation and exerts oncogenic functions in melanoma progression." (PMID 33293474, 2020). "MITF is a lineage-restricted regulator in melanocytes that is positively associated with melanoma proliferation, and also suppressed invasion and metastasis." (PMID 32332858, 2020). "For example, MITF sumoylation was shown to affect cell senescence and seems to be associated with development of melanoma." (PMID 32605090, 2020). "Another example is miR-137, which regulates the expression of MITF in healthy melanocytes and was the first miRNA described to be associated with melanoma development." (PMID 31906510, 2020). "ZEB2 drives MITF expression and is associated with a differentiated/proliferative melanoma cell state." (PMID 32796736, 2020). "Our analysis revealed that, upon MITF depletion, the overall expression of Rec-coding loci, including ERVK6, was down, indicating that MITF and Rec expression levels are tightly associated in melanoma cells." (PMID 33202765, 2020).
melanoma (continued). "On the other hand, high expression of proliferative marker MITF is associated with the less frequent presence of CAFs in the melanoma TME, which shows an even more complex link between the cancer plasticity and its niche." (PMID 33171792, 2020). "Dedifferentiation of melanoma tumor cells through the loss of MITF has been indicated as an immune evasion mechanism." (PMID 32245160, 2020). "sFRP2 promotes the loss of APE1, a key redox effector, in melanoma cells by decreasing the levels of β-catenin and microphthalmia-associated transcription factor (MITF)." (PMID 32411704, 2020). "Accumulating evidence suggests that a key determinant of melanoma phenotype is the expression and activity of the microphthalmia-associated transcription factor (MITF)." (PMID 33396270, 2020). "NME1LOW cells did not exhibit altered expression of mRNAs associated with differentiated melanocytes or transcripts encoding the putative melanoma virulence factors MITF, AXL, and JARID1b." (PMID 32029850, 2020). "In particular, a reduced expression of ZEB2 and SNAIL2, in favor of an increased expression in ZEB1 and TWIST1, has been linked to MITF downregulation, E-cadherin loss and increased invasive properties of human melanoma cells." (PMID 33121001, 2020). "The melanoma-associated cluster includes lineage specific genes, such as MITF and MLANA, as well as markers associated with resistance to target therapy in melanoma, such as AXL and NFKB." (PMID 33202944, 2020). "BRN2 has therefore been associated with the invasive, drug-resistant melanoma cell population, whereas MITF with the proliferative, drug-sensitive population." (PMID 32632141, 2020). "MITF-M is the melanocyte-specific isoform of Microphthalmia-associated Transcription Factor (MITF) in human melanoma." (PMID 32605315, 2020). "MITF was previously shown to be associated with prognosis in patients with melanoma and renal cell carcinoma." (PMID 33371469, 2020). "The microphthalmia-associated transcription factor (MITF) is a well-known oncogene of melanoma, which is negatively associated with the invasion properties of cancer cells." (PMID 32344837, 2020). "We did not choose BCL2A1, although its basal expression was highly upregulated in DMBC21 compared with DMBC11 cells, as BCL2A1 is also a target of microphthalmia-associated transcription factor (MITF), which is a melanoma-specific protein." (PMID 32466509, 2020). "On the other hand, a melanoma-derived Wnt5a ligand decreases the expression of MITF, which leads to downregulation of the melanoma-associated antigen level and promotes a more “migratory” phenotype." (PMID 33171792, 2020). "Functional studies highlighted that the MITF gene has potential involvement in porcine melanoma biology; however, direct association of this gene with melanoma development was not confirmed." (PMID 31717496, 2019). "Mutations in the MITF gene are found not only in melanomas but also in other cancers, such as renal cell carcinoma." (PMID 31717496, 2019). "Here we show that lncRNAs are also important components of MITF-SOX10-driven transcriptional programmes and identify 245 candidate melanoma-associated lncRNAs whose loci are co-bound by MITF and SOX10." (PMID 31881017, 2019). "Consistent with this, in melanocytes the lineage-determining microphthalmia-associated transcription factor (MITF) that controls melanoma differentiation, proliferation, and invasion can regulate expression of DDR genes." (PMID 30804224, 2019). "Both melanosome synthesis and melanogenesis pathway are regulated in melanoma by the melanocyte-inducing transcription factor/micropthalmia-associated transcription factor (MITF)." (PMID 31547367, 2019).